BBS2 (Bardet-Biedl syndrome 2)
Description:
The BBSome complex is thought to function as a coat complex required for sorting of specific membrane proteins to the primary cilia. The BBSome complex is required for ciliogenesis but is dispensable for centriolar satellite function. This ciliogenic function is mediated in part by the Rab8 GDP/GTP exchange factor, which localizes to the basal body and contacts the BBSome. Rab8(GTP) enters the primary cilium and promotes extension of the ciliary membrane. Firstly the BBSome associates with the ciliary membrane and binds to RAB3IP/Rabin8, the guanosyl exchange factor (GEF) for Rab8 and then the Rab8-GTP localizes to the cilium and promotes docking and fusion of carrier vesicles to the base of the ciliary membrane. The BBSome complex, together with the LTZL1, controls SMO ciliary trafficking and contributes to the sonic hedgehog (SHH) pathway regulation. Required for proper BBSome complex assembly and its ciliary localization.
Synonyms: BBS; RP74
Tractability: Antibody: its Gene Ontology location is reachable by antibodies, with medium confidence. PROTAC: ubiquitination databases record sites on it; its protein half-life has been measured.
Gene: Protein-coding gene on chromosome 16 (56,465,640 to 56,582,667, reverse strand). Ensembl gene ENSG00000125124.
Subcellular location: Cell projection, cilium membrane; Cytoplasm; Cytoplasm, cytoskeleton, microtubule organizing center, centrosome, centriolar satellite
Subcellular location (Human Protein Atlas): Vesicles; Primary cilium transition zone
Pathways (Reactome):
Organelle biogenesis and maintenance: BBSome-mediated cargo-targeting to cilium
Gene Ontology:
Molecular function: protein binding; RNA polymerase II-specific DNA-binding transcription factor binding
Biological process: Golgi to plasma membrane protein transport; visual perception; adult behavior; brain morphogenesis; cerebral cortex development; cilium assembly; fat cell differentiation; hippocampus development; intracellular protein localization; melanosome transport; negative regulation of appetite by leptin-mediated signaling pathway; negative regulation of multicellular organism growth; photoreceptor cell maintenance; regulation of cilium beat frequency involved in ciliary motility; sperm axoneme assembly; striatum development; non-motile cilium assembly
Cellular component: BBSome; ciliary basal body; ciliary membrane; ciliary transition zone; motile cilium; cytosol; membrane; neuron projection; centriolar satellite; cytoplasm; microvillus; stereocilium
Genetic constraint (gnomAD): Loss-of-function variants: 60 observed, 83.36 expected, observed/expected ratio (o/e) 0.72, 90% interval 0.58 to 0.89. The upper end of that interval is the gene's LOEUF score, 0.89, which puts it in group 3 of 6, group 1 being the genes least tolerant of losing a copy. Missense variants: 776 observed, 942.49 expected, observed/expected ratio (o/e) 0.82, 90% interval 0.77 to 0.87. Synonymous variants: 301 observed, 344.65 expected, observed/expected ratio (o/e) 0.87, 90% interval 0.79 to 0.96.
Gene-disease validity (ClinGen):
ClinGen rates the evidence that BBS2 causes each of these diseases.
BBS2-related ciliopathy (autosomal recessive): Definitive. Any ciliopathy caused by variants in the BBS2 gene.
Homologues: Orthologues: chimpanzee BBS2 (99% identical), macaque BBS2 (98% identical), dog BBS2 (94% identical), rabbit BBS2 (92% identical), pig BBS2 (92% identical), guinea pig BBS2 (90% identical), mouse Bbs2 (90% identical), rat Bbs2 (90% identical), tropical clawed frog bbs2 (78% identical), zebrafish bbs2 (74% identical), Caenorhabditis elegans bbs-2 (32% identical).